KCNMB2-AS1 (KCNMB2 antisense RNA 1)
Synonyms: RP11-385J1.2
Gene: Long non-coding RNA gene on chromosome 3 (178,526,505 to 178,948,804, reverse strand). Ensembl gene ENSG00000237978.
Diseases named in the same sentence as KCNMB2-AS1 in open-access papers:
KCNMB2-AS1 is named in the same sentence as 1 disease in open-access papers, as found by Europe PMC text mining. Sharing a sentence is not in itself a finding about the gene and the disease.
KCNMB2-AS1 shares sentences with these, for which no sentence is quoted: cervical cancer (1 paper).